CLEC19A (C-type lectin domain containing 19A)
Tractability: Antibody: UniProt places it where antibodies can reach, with high confidence; UniProt predicts a signal peptide or a membrane-spanning region; its Gene Ontology location is reachable by antibodies, with medium confidence.
Gene: Protein-coding gene on chromosome 16 (19,285,731 to 19,322,145, forward strand). Ensembl gene ENSG00000261210.
Subcellular location: Secreted
Gene Ontology:
Molecular function: protein binding
Cellular component: extracellular region
Genetic constraint (gnomAD): Loss-of-function variants: 22 observed, 27.19 expected, observed/expected ratio (o/e) 0.81, 90% interval 0.58 to 1.15. The upper end of that interval is the gene's LOEUF score, 1.15, which puts it in group 5 of 6, group 1 being the genes least tolerant of losing a copy. Missense variants: 224 observed, 230.43 expected, observed/expected ratio (o/e) 0.97, 90% interval 0.87 to 1.09. Synonymous variants: 89 observed, 90.69 expected, observed/expected ratio (o/e) 0.98, 90% interval 0.83 to 1.17.
Homologues: Orthologues: chimpanzee CLEC19A (99% identical), macaque CLEC19A (88% identical), rabbit CLEC19A (87% identical), zebrafish clec19a (66% identical), tropical clawed frog clec19a (63% identical), Caenorhabditis elegans clec-150 (22% identical). Paralogues in human: REG3A (28% identical), REG1B (26% identical), REG3G (26% identical), REG1A (25% identical), REG4 (22% identical).
Diseases named in the same sentence as CLEC19A in open-access papers:
CLEC19A is named in the same sentence as 6 diseases in open-access papers, as found by Europe PMC text mining. Sharing a sentence is not in itself a finding about the gene and the disease. The quoted sentences say what the papers report.
astrocytoma (1 paper, 2024). "The results corroborated that CLEC19A expression is statistically significantly reduced in aggressive glioma cell lines including A172, U87, and C6 relative to 1321N1 low-grade astrocytoma cells (p < 0.05)." (PMID 38167030, 2024).
brain tumor (1 paper, 2024). "Collectively, these results indicate that CLEC19A overexpression can inhibit the tumorigenicity of C6 glioma cells in vivo, and significantly decreases brain tumor volume size in the glioma rat model." (PMID 38167030, 2024). "Our in vivo data revealed that the overexpression of CLEC19A significantly decreases brain tumor volume size and suppresses tumor growth in a glioma rat model." (PMID 38167030, 2024). "We observed that the overexpression of CLEC19A significantly decreased brain tumor volume size in the rat model of glioma, which indicated a putative tumor suppressor gene function of the CLEC19A gene." (PMID 38167030, 2024). "Furthermore, overexpression of CLEC19A decreased brain tumor volume size in the rat model of glioma." (PMID 38167030, 2024).
glioma (1 paper, 2024). A benign or malignant brain and spinal cord tumor that arises from glial cells (astrocytes, oligodendrocytes, ependymal cells). "Results obtained from several in vitro readouts showed that CLEC19A overexpression in U87 and C6 glioma cell lines is associated with the inhibition of cell proliferation, viability, and migration." (PMID 38167030, 2024). "Furthermore, flow cytometry results revealed that CLEC19A overexpression was associated with significant cell cycle arrest and promotion of apoptosis in glioma cell lines." (PMID 38167030, 2024). "Also, the overexpression of CLEC19A was shown to be associated with the promotion of apoptosis and arrest of the cell cycle in the sub-G1 phase in the glioma cell lines." (PMID 38167030, 2024). "To evaluate the effect of CLEC19A overexpression on glioma cell migration in vitro, we explored its impact on the migration of U87 and C6 cells using a wound healing assay, transwell test, and Western blot analysis." (PMID 38167030, 2024). "Our in-silico analysis using TCGA data and measuring CLEC19A expression level by qRT-PCR determined significantly lower expression of CLEC19A in human glioma tissues compared to healthy brain tissues." (PMID 38167030, 2024). "Considering that the CLEC19A gene is expressed in the human brain and that its expression is likely decreased in the brain of glioma patients, we sought to study the CLEC19A gene in GBM." (PMID 38167030, 2024). "In this study, we analyzed the expression of CLEC19A from TCGA data of patients with LGGs (low-grade gliomas) and GBMs." (PMID 38167030, 2024). "Our Experimental analyses have shown that CLEC19A notably reduced in glioma tissues and cell lines, verified by in-silico data." (PMID 38167030, 2024). "Next, we examined the potential impact of CLEC19A overexpression on the cell cycle and apoptosis of glioma cell lines." (PMID 38167030, 2024). "Based on our study, CLEC19A protein has calcium binding sites and its expression decreased both in mRNA and protein levels in glioma." (PMID 38167030, 2024). "We demonstrated that cell proliferation and migration were significantly decreased by overexpression of CLEC19A in U87 and C6 glioma cell lines." (PMID 38167030, 2024). "Consistent with previous findings, we observed that the overexpression of CLEC19A significantly suppressed the proliferative potential of glioma cells through the inhibition of PI3K, AKT1, and NF-κB." (PMID 38167030, 2024). "Together, these results provide important insights that the overexpression of CLEC19A could inhibit cell proliferation, viability, and migration and also induce cell apoptosis in glioma cells." (PMID 38167030, 2024). "Interestingly, using a glioma rat model we could substantiate that CLEC19A overexpression suppresses glioma tumor growth." (PMID 38167030, 2024). "Based on NCBI and the Human protein atlas data CLEC19A has the highest expression in brain tissue compared to other human tissues, GBM and LGG RNAseq data were obtained from the TCGA database to evaluate CLEC19A expression in glioma and normal tissues." (PMID 38167030, 2024). "Given the fact that CLEC19A has the highest expression in the normal human brain compared to other human tissues (HPA project) and is expressed at a low level in glioma, we investigate the role of CLEC19A and its function in glioma cells through in vitro and in vivo experiments." (PMID 38167030, 2024).
cancer (1 paper, 2024). A tumor composed of atypical neoplastic, often pleomorphic cells that invade other tissues. "An increase in the TIPM3 and RECK protein levels (3.21- and 1.35-fold increase respectively) and a decrease in the MMP2 protein level (0.46-fold) indicated that overexpression of CLEC19A reduced the ability of U87 cancer cell migration." (PMID 38167030, 2024). "In regard to these results, some of the members of the C-type lectin superfamily like CLEC19A consist of CLEC10A, CLEC2, and CLEC9A suppressed cell proliferation, migration, and invasion, and also cell cycle arrest, and promoted apoptosis in cancer cells." (PMID 38167030, 2024).
tumor (1 paper, 2024). "The MRI results revealed that overexpression of CLEC19A in rat brains could statistically significantly suppress tumor growth rate in comparison to untreated and mock groups." (PMID 38167030, 2024). "In summary, this study suggests that CLEC19A overexpression reduces tumor cell proliferation and migration by suppressing PI3K/AKT/NF-κB and VEGF/MMPs signaling pathways and promotes cell apoptosis and arrested cells in the sub-G1 phase in U87 and C6 cell lines." (PMID 38167030, 2024). "Analyzing samples from the TCGA dataset consisting of adjacent tumor samples, LGG, and GBM tissues demonstrated that CLEC19A gene expression statistically significantly decreased in LGG and GBM tissues compared to adjacent normal brain tissues (p < 0.0001)." (PMID 38167030, 2024). "To ascertain this, we next investigated the expression of the CLEC19A gene in samples from LGG (n = 8), GBM (n = 7), and adjacent tumor samples (n = 4) using qRT-PCR." (PMID 38167030, 2024).
CLEC19A also shares sentences with these, for which no sentence is quoted: glioblastoma (1 paper).